SOX7 (SRY-box transcription factor 7)
Description:
Binds to and activates the CDH5 promoter, hence plays a role in the transcriptional regulation of genes expressed in the hemogenic endothelium and blocks further differentiation into blood precursors (By similarity). May be required for the survival of both hematopoietic and endothelial precursors during specification (By similarity). Competes with GATA4 for binding and activation of the FGF3 promoter (By similarity). Represses Wnt/beta-catenin-stimulated transcription, probably by targeting CTNNB1 to proteasomal degradation. Binds the DNA sequence 5'-AACAAT-3'.
Tractability: No criterion of Open Targets' tractability assessment is met for any kind of drug.
Gene: Protein-coding gene on chromosome 8 (10,723,768 to 10,730,511, reverse strand). Ensembl gene ENSG00000171056.
Subcellular location: Nucleus; Cytoplasm
Subcellular location (Human Protein Atlas): Nuclear speckles; Golgi apparatus
Pathways (Reactome):
Signal Transduction: Deactivation of the beta-catenin transactivating complex
Gene Ontology:
Molecular function: DNA-binding transcription factor activity; protein binding; sequence-specific double-stranded DNA binding; DNA-binding transcription activator activity, RNA polymerase II-specific; DNA-binding transcription factor activity, RNA polymerase II-specific; RNA polymerase II cis-regulatory region sequence-specific DNA binding; transcription cis-regulatory region binding; sequence-specific DNA binding
Biological process: endoderm formation; negative regulation of DNA-templated transcription; cell differentiation; positive regulation of transcription by RNA polymerase II; anatomical structure formation involved in morphogenesis; tissue development
Cellular component: cytoplasm; nucleus; chromatin; nucleoplasm
Genetic constraint (gnomAD): Loss-of-function variants: 19 observed, 20.3 expected, observed/expected ratio (o/e) 0.94, 90% interval 0.65 to 1.37. The synonymous counts are far from expectation, so gnomAD's model fits this gene poorly and the ratio says little. Missense variants: 702 observed, 517.63 expected, observed/expected ratio (o/e) 1.36, 90% interval 1.27 to 1.44. Synonymous variants: 327 observed, 237.49 expected, observed/expected ratio (o/e) 1.38, 90% interval 1.26 to 1.51.
Gene-disease validity (ClinGen):
ClinGen rates the evidence that SOX7 causes each of these diseases.
congenital heart disease (autosomal dominant): Limited. A heart disease that is present at birth.
Homologues: Orthologues: chimpanzee SOX7 (99% identical), dog SOX7 (95% identical), pig SOX7 (94% identical), rat Sox7 (88% identical), mouse Sox7 (87% identical), guinea pig SOX7 (87% identical), rabbit SOX7 (76% identical), tropical clawed frog sox7 (65% identical), zebrafish sox7 (57% identical), Drosophila melanogaster Sox14 (26% identical), Drosophila melanogaster Sox21a (20% identical), Drosophila melanogaster Sox102F (18% identical), and 2 more. Paralogues in human: SOX17 (41% identical), SOX18 (39% identical), SOX9 (24% identical), SOX4 (23% identical), CFAP65 (23% identical), SOX1 (22% identical), SOX30 (22% identical), SOX11 (22% identical), SOX3 (22% identical), SOX12 (21% identical), SOX10 (21% identical), SOX8 (21% identical), and 8 more.
Diseases named in the same sentence as SOX7 in open-access papers:
SOX7 is named in the same sentence as 84 diseases in open-access papers, as found by Europe PMC text mining. Sharing a sentence is not in itself a finding about the gene and the disease. The quoted sentences say what the papers report.
lung cancer (22 papers, 2009 to 2025). A malignant neoplasm involving the lung. "The mechanism underlying the down-regulation of SOX7 expression in lung cancer was explored." (PMID 23557216, 2013). "In many human cancers, the expression of SOX7 is downregulated, and overexpression of SOX7 protein can inhibit the proliferation of colon and lung cancer cells." (PMID 39227479, 2024). "This underscores the tumor-suppressive role of SOX7 in BCa, akin to its effects observed in breast and lung cancers." (PMID 39227479, 2024). "In lung cancer, miR-24-3p is upregulated and targets SOX7 to promote cancer cell development in vitro and in vivo." (PMID 36814556, 2023). "The overexpression of MEG3 also enhanced cisplatin sensitivity in cisplatin-resistant lung cancer cells by regulating the miR-21-5p/SOX7 axis, in vitro and in vivo models, impeding cell proliferation, and inducing apoptosis." (PMID 36778005, 2023). "In lung cancer, miR-24 strengthened tumor proliferation and migration by directly targeting SOX7 in tumor cells and in a xenograft mouse model." (PMID 33550881, 2021). "MEG3 (Maternally Expressed 3)-imprinted long non-coding RNA gene knockdown in lung cancer leads to enhanced antiproliferative and proangiogenic features of those cancer cells by affecting the SOX7 transcript." (PMID 33152990, 2020). "Hypermethylation of the SOX7 gene is highly associated with a poor prognosis in myelodysplastic syndrome (MDS) and lung cancer patients." (PMID 33152990, 2020). "The miR-616 molecule regulates the expression of the downstream targets of SOX7 in lung cancer cells (p-Rb, Cyclin-D1 and c-Myc)." (PMID 33152990, 2020). "Panobinostat elevates Sry-box transcription factor 7 (SOX7) expression and suppresses lung cancer cell proliferation." (PMID 33117804, 2020). "miR-935 has already been reported to downregulate SOX7 expression in liver, gastric and lung cancers." (PMID 33152990, 2020). "For example, the decreased expression of Sox7 is correlated with poor prognosis in lung cancer patients." (PMID 26871472, 2016). "SOX7 was reported to be downregulated in lung cancer and forced-expression of SOX7 reduces cell proliferation, increases sub-G1 phase of cell cycle and increases apoptosis of non-small cell lung cancer (NSCLC) cells." (PMID 24558429, 2014). "We provide evidence that SOX7 behaves as a tumor suppressor in lung tissue and its expression is either low or silenced in the majority of lung cancers." (PMID 23557216, 2013). "To study the effect of SOX7 expression on the cell cycle, we used H23 and H1299 human lung cancer cell lines stably expressing either SOX7 or GFP (used as control)." (PMID 23557216, 2013). "It was demonstrated that SOX7 was a tumor suppressor in lung cancer." (PMID 39346732, 2024). "Additionally, the Food and Drug Administration (FDA)-approved pan-HDAC inhibitor (Panobinostat) can elevate SOX7 expression in lung cancer cell lines." (PMID 33152990, 2020). "miR-9 is upregulated and SOX7 is downregulated in lung cancer cell lines and tissues." (PMID 33152990, 2020). "miR-24-3p promotes tumor growth in xenograft mice by targeting SOX7, which suggests that this miRNA molecule could play a role as an oncomiR in lung cancer tumorigenesis by regulating SOX7 expression." (PMID 33152990, 2020). "In lung cancer cells, miR-24-3p could promote cell proliferation and migration; it also accelerates tumor growth in xenograft mice by directly binding to SRY-box transcription factor 7 (SOX7)." (PMID 31652908, 2019). "For example, SOX7 is up-regulated in pancreatic cancer cell lines and primary gastric cancer cases, but down-regulated in primary colorectal tumors, prostate cancer, lung cancer and breast cancer." (PMID 24816720, 2014). "Furthermore, SOX7 functions as a tumor suppressor in lung cancers, endometrial cancer, colorectal cancer, prostate cancer and breast cancer." (PMID 24558429, 2014).
lung cancer (continued). "SOX7, a member of the SOX-F subfamily encoding transcription factors that have a pivotal role in cardiovascular development,has been implicated as a tumor suppressor in a variety of human cancers, e.g., colorectal, prostate, breast, liver and lung cancers." (PMID 25297608, 2014). "Sox7 mRNA is highly expressed in adult lung but down-regulated in lung cancer." (PMID 19812696, 2009). "Moreover, miR-24-3p promoted cell migration and proliferation in lung cancer by targeting SOX7." (PMID 35456441, 2022). "Thus, SOX7 was suggested to be a novel tumour suppressor in lung cancer." (PMID 28266181, 2017). "Indeed, SOX7 is up-regulated in pancreatic cancer cell lines and primary gastric cancer cases, but down-regulated in primary colorectal tumors, prostate cancer, lung cancer and breast cancer, indicating that the role of SOX7 in tumorigenesis is depending on tumor type." (PMID 24816720, 2014). "Additionally, SOX7 may have potential usage as an independent prognostic marker in prostate and lung cancers as well as MDS patients." (PMID 25297608, 2014). "Studies have found that miR-24-3p can promote lung cancer cell migration and proliferation by targeting SOX7 (SRY-box transcription factor 7)." (PMID 35203213, 2022). "In addition to miR-21-5p/SOX7, the downregulation of MEG3 increases cisplatin resistance of lung cancer cells via activation of the WNT/beta-catenin signaling pathway." (PMID 36778005, 2023). "Unlike SOX18 expression, SOX7 expression has been shown to be decreased in lung cancers, which correlates with a poor patient prognosis." (PMID 33152990, 2020). "In lung cancer, MEG3 could enhance the chemosensitivity through regulation the WNT/beta catenin signaling pathway and miR-21-5p/SOX7 axis." (PMID 31488093, 2019).
breast carcinoma (12 papers, 2014 to 2024). "Hypermethylation-mediated silencing of the SOX7 promoter is associated with greater carcinogenesis in breast cancer." (PMID 38132479, 2023). "SOX7 downregulation and the mechanism underlying its reduced expression have also been very well described on breast cancer cell lines and tumors." (PMID 33152990, 2020). "Its over-expression triggered proliferation and anchorage-independent growth in cells and acted as an oncomiR in breast cancer initiation through associating with cyclin D1 and c-Myc and downregulating SOX7, a tumor suppressor and a downstream target of miR-492." (PMID 36539576, 2022). "Sox7 downregulation has also been linked to breast cancer in humans." (PMID 35573279, 2022). "Clinicopathological data also showed that SOX7 was significantly associated with disease progression and so may be used as an independent predictor of breast cancer." (PMID 27188720, 2016). "In the top motif enriched in downregulated peaks, Sox7 was reported to play inhibitory roles related to cellular proliferation, migration, and invasion in breast cancer." (PMID 36579891, 2022). "Similar to what happens in other types of cancer, SOX7 acts as a tumor suppressor in breast cancer pathogenesis." (PMID 33152990, 2020). "Promoter methylation, as a major mechanism of SOX7 downregulation, has been identified in six of the nine breast cancer cell lines, although the frequency of methylation was relatively low in comparison to the frequency observed in prostate and colon cancers." (PMID 33152990, 2020). "To choose potential target genes of SOX7 in breast cancer, we took both our SOX7 microarray data and a gene array dataset of 759 breast cancer patients into consideration." (PMID 29757932, 2018). "In the current study, we systematically investigated SOX7-mediated transcription in breast cancer MDA-MB-231 cells, which have an undetectable endogenous SOX7 expression, and discovered TRIB3 and MTHFD2 as its repressed genes." (PMID 29757932, 2018). "Our study and those conducted by others, demonstrated that promoter DNA methylation played a major role for SOX7 downregulation in colon, prostate, breast cancers, and myelodysplastic syndrome." (PMID 29757932, 2018). "Our group revealed that SOX7 downregulation negatively correlated with distant metastasis-free survival in a gene array of 674 breast cancer patients." (PMID 29757932, 2018). "We next evaluated the contributions of these SOX7 target genes to its tumor suppressive role in breast cancer." (PMID 29757932, 2018). "We reported a tumor suppressive role of SOX7 and its downregulation by DNA methylation in breast cancer." (PMID 29757932, 2018). "We revealed SOX7-mediated gene expression profile in breast cancer cells using microarray chips and discovered multiple altered signaling pathways." (PMID 29757932, 2018). "SOX7 downregulation has been reported for colon, prostate, lung, breast cancers, and myelodysplastic syndrome (a typical prelude to acute myeloid leukemia)." (PMID 29757932, 2018). "When combinatorially analyzing the microarray data with a gene array dataset from 759 breast cancer patients, we identified four genes as potential targets of SOX7 and validated them by quantitative PCR and chromatin immunoprecipitation assays." (PMID 29757932, 2018). "Clinicopathological analysis demonstrated that the down-regulated SOX7 was significantly correlated with advanced stages and poorly differentiated breast cancers." (PMID 27188720, 2016). "We found that the expression of SOX7 was significantly reduced in breast cancer and this effect was positively correlated with AXIN2." (PMID 27188720, 2016). "SOX7 as a tumor suppressor belongs to the SOX F gene subfamily and is associated with a variety of human cancers, including breast cancer, but the mechanisms involved are largely unclear." (PMID 27188720, 2016).
breast carcinoma (continued). "In this study, we investigated the changes and possible roles of SOX7 in breast cancer by analyzing its expression levels using bioinformatics tools and then experimentally validated the results with clinical tissues." (PMID 27188720, 2016). "SOX7 is frequently down-regulated in many human cancers, such as prostate, colon, lung, and breast cancers, and its reduced expression often correlates with poor prognoses." (PMID 25297608, 2014). "Therefore, the study revealed that a direct SOX7 supression is instrumental in the pretumorigenic phenotypes observed in breast cancer cells upon the over-expression of the oncomiR, miR-49245." (PMID 36539576, 2022). "Changes in the regulatory sequence upstream of SOX7 may be one factor responsible for these changes in expression related to breast cancer." (PMID 35573279, 2022). "Moreover, the downregulation of SOX7 expression in breast cancers is mediated by additional epigenetic and genetic mechanisms such as histone deacetylation." (PMID 33152990, 2020). "This could be due to the fact that breast cancer shows high heterogeneity and SOX7 methylation occurs only at some specific stages of tumor development." (PMID 33152990, 2020). "Overexpressed SOX7 inhibited cell proliferation and colony formation of prostate, breast, and colon cancer cells, induced apoptosis in colon cancer cells, and inhibited tumor formation in breast cancer." (PMID 29757932, 2018). "The rationale is that if a target gene is essential to SOX7-mediated tumor suppression, reversely changing the expression of this gene will counteract the antiproliferative effects of ectopic SOX7 expression on breast cancer cells." (PMID 29757932, 2018). "Taken together, these findings suggest that SOX7 might be an independent biomarker in breast cancer." (PMID 27188720, 2016). "Moreover, the SOX7 protein expression was more frequently detected in the well and moderately differentiated breast cancer than in poorly differentiated breast cancer (G1–G2; 59/74, p < 0.01)." (PMID 27188720, 2016). "Postulating that some genes in the Wnt/β-catenin pathway might be co-expressed with SOX7 and contribute to tumor suppressing, we compared the gene expression profiles between the 40 breast cancer specimens and the seven normal breast tissues." (PMID 27188720, 2016). "In breast cancer, Sui and colleagues for the first time reported that SOX7 is likely regulated by multiple mechanisms and may potentially serve as a prognostic marker for breast cancer." (PMID 27188720, 2016). "Furthermore, SOX7 has been supposed to be a suppressor to miR-492, which represents a potential onco-miR and participates in breast cancer carcinogenesis." (PMID 27188720, 2016). "Numerous studies also suggest that promoter methylation might be an important mechanism of SOX7 down-regulation in breast cancer and MDS." (PMID 25297608, 2014). "Studies undertaken by our group previously demonstrated that many breast cancer cell lines, including MDA-MB-231, showed undetectable or very low levels of both SOX7 protein and mRNA." (PMID 29757932, 2018). "Collectively, these data strongly suggest that SOX7 activates SPRY1 and SLIT2, but inhibits MTHFD2 and TRIB3 in breast cancer." (PMID 29757932, 2018). "Firstly, using gene expression files, we found that the expression of SOX7, SOX17 and SOX18 was significantly reduced, whereas SOX4 was markedly increased in breast cancer tissues compared to normal tissues." (PMID 27188720, 2016). "Our results also showed Smad7 as the target of SOX7 and AXIN2 in controlling breast cancer progression through the Wnt/β-catenin signaling pathway." (PMID 27188720, 2016).
breast carcinoma (continued). "We compared the expression levels of SOX7 and other SOX family members using gene expression profiles by MATLAB (Matrix Laboratory) between forty breast cancers and seven controls in GSE3744, with the FDR (False Discovery Rate) being controlled." (PMID 27188720, 2016). "Our results also suggested Smad7 to be the target of SOX7 and AXIN2 in controlling breast cancer progression through the Wnt/β-catenin signaling pathway." (PMID 27188720, 2016). "We found that the expression levels of SOX7, SOX17 and SOX18 were reduced significantly in breast cancer tissues compared to normal controls." (PMID 27188720, 2016). "We compared the expression levels of SOX7 and other co-expressed genes in the Wnt/β-catenin pathway and found that the expression of SOX7, SOX17 and SOX18 was all reduced significantly in the breast cancer tissues compared to normal controls." (PMID 27188720, 2016). "In the current study, we investigated the interactions between SOX7 and AXIN2 in their co-regulation on the Wnt/β-catenin signal pathway, using clinical specimens and microarray gene expression data from the GEO database, for their roles in breast cancer." (PMID 27188720, 2016). "In conclusion, we demonstrate here, for the first time, that SOX7 plays the role of tumor suppressor on β-catenin by targeting Smad7, together with AXIN2 as a portential co-regulator of the Wnt/β-catenin signaling pathway in controlling breast cancer progression." (PMID 27188720, 2016). "Based on the findings in this study, we propose that the significantly reduced expression of both SOX7 and AXIN2 may jointly facilitate the pathogenesis of breast cancer, possibly through regulating the β-catenin by not-direct as well as direct ways." (PMID 27188720, 2016).